FOXC1 (forkhead box C1)
Diseases named in the same sentence as FOXC1 in open-access papers (continued):
Sharing a sentence is not in itself a finding about the gene and the disease.
breast carcinoma (continued). "In breast cancer, several lines of evidence have implicated overexpression of EZH2 and repression of tumor suppressors such as KRT5, KRT6, CDH3, RAD51 paralogs, CDKN1C, FOXC1, Wnt/β-catenin signaling (c-Myc, Cyclin D1, Axin2), RKIP and KLF2." (PMID 27835578, 2016). "In breast cancer, we have demonstrated that FOXC1 plays a role in proliferation in BRCA1-mutant BLBC cells, and prior studies have demonstrated a critical role for FOXC1 in the functional properties of BLBC, driving metastasis, epithelial-mesenchymal transition phenotype, and tumorigenesis." (PMID 27708239, 2016). "FOXC1, a prognostic biomarker of basal-like breast cancer patients is a key regulator of NF-kappaB signaling pathways in basal-like breast cancer cells and promotes breast cancer invasion." (PMID 26618778, 2015). "Interestingly, recent studies have demonstrated that basal-like breast cancer pathogenesis can be inhibited by the repressive activity of Gata-3 on FOXC1 expression and by the silencing activity of EZH2." (PMID 25962646, 2015). "In addition to its role in embryonic development, FOXC1 has also been shown to serve as a biomarker for breast cancer." (PMID 25875420, 2015). "There was also a considerable increase in the expression of others genes described as stem cell markers and expressed in CD44high fractions of normal and breast cancer tissues, including FOXC1(∼11-fold), IGFBP7 (∼8.5-fold), PROCR (∼8.2-fold), LEF1 (∼6.7-fold) and ZEB1 (∼6.6-fold)." (PMID 24498388, 2014). "The FOXC1 methylation status might be a widely applicable prognostic factor for breast cancer patients while the methylation status of ABCB1 and GSTP1 might be a predictive factor for doxorubicin and perhaps anthracycline treatment in general." (PMID 20338046, 2010). "Moreover, it was reported that under the catalysis of polycomb reactive complex 2 (PRC2), EZH2 can inhibit the transcription of its target gene through the trimethylation of Lys-27 on histone 3 (H3K27me3), thus controlling the expression of FOXC1 in breast cancer." (PMID 40003882, 2025). "However, further investigation is required to determine whether FOXC1 directly or indirectly regulates L1CAM in breast cancer cells." (PMID 38183514, 2024). "Furthermore, FOXC1 is found to be highly expressed in basal-like breast cancer (BLBC)." (PMID 37626655, 2023). "Foxc1 had been verified to induce the nuclear translocation of NF-κB through promoting the phosphorylation of IκB both in mice airway smooth muscle cells and human basal-like breast cancer cells and the PI3K/AKT signaling pathway in ovalbumin-induced asthmatic mice." (PMID 34930462, 2021). "Thus, while the preponderance of evidence supports elevated expression of FOXC1 being an accurate predictor of adverse clinical outcomes, the two notable exceptions include ovarian cancer and Luminal B molecular subtype of breast cancer where elevated expression of FOXC1 predicts good prognosis." (PMID 34540690, 2021). "Indeed, while some studies argue for a role of O-GlcNAcylation in the regulation of EZH2 stability and catalytic activity, others propose that the glycosylation rather regulates EZH2 recruitment to some of its target genes such as FOXC1 in breast cancer cells or IL-15 in muscle." (PMID 33126652, 2020). "Of these, perhaps the most important is the FOXC1 forkhead transcription factor (TF), which has been shown recently to have profound and critical roles in several disparate cancer types following its initial identification as a key prognostic indicator of basal-like breast cancer (BLBC)." (PMID 29487724, 2018). "Moreover, EMT, which plays a key role in the generation and maintenance of cancer stem cells was proposed to be activated by FOXC1 in breast cancer which might explain part of this role of FOXC1 in cancer cell stemness." (PMID 29487724, 2018).
breast carcinoma (continued). "Samples of breast cancer (>5 cm) are considered stage T3-T4 tumors, and samples (<5 cm) are considered stage T1-T2 tumors; 75 samples were from stage T1-T2, 14 samples were from stage T3-T4, and the proportion of FOXC1-positive tumors in each group was 56% (42/75) and 42.8% (6/14), respectively." (PMID 30564302, 2018). "We have further established the potential of using FOXC1 as a prognostic biomarker in specific breast cancer subtypes and identified a pharmacological means to suppress metastatic progression in a subtype of breast cancer for which there is unmet clinical need." (PMID 29959321, 2018). "Moreover, FOXC1 transgenic mice may serve as a clinically relevant model, together with other breast cancer mouse models, to address the poorly understood mechanism of BLBC tumorigenesis and progression." (PMID 29070831, 2017). "Another EMT pathway, Wnt/β-Catenin, is also the common mechanism for FOXC1, FOXF2, and FOXM1 to regulate breast cancer EMT." (PMID 40003882, 2025). "In breast cancer, especially BLBC and triple-negative breast cancer (TNBC), FOXC1 plays an important role in promoting cell proliferation, migration, and EMT." (PMID 40003882, 2025). "In particular, FOXC1, FOXM1, and FOXO3 can all interact with BRCA1 and regulate the genome stability of breast cancer cells." (PMID 40003882, 2025). "FOXC1 and FOXF2 have interactions with TGF-β/Smad, which indicates their role in breast cancer cell EMT." (PMID 40003882, 2025). "For example, FOXA1, FOXA2, FOXC1, and FOXO3 can all interact with the PI3K/AKT/mTOR pathway and eventually regulate breast cancer cell proliferation." (PMID 40003882, 2025). "The ChIP assay conducted by the researchers demonstrated the ability of FOXC1 to bind to the CXCR4 promoter, thereby enhancing its fold enrichment in breast cancer." (PMID 40003882, 2025). "Much like FOXC1, FOXF2 also exhibits a dual role in breast cancer, with its function significantly differing between the luminal and basal types of the disease." (PMID 40003882, 2025). "A correlation analysis was performed using publicly available mRNA profiles from two cohorts of breast cancer patients to investigate the relationship between L1CAM and FOXC1." (PMID 38183514, 2024). "Previous research supports the notion that FOXC1 functions as a negative prognostic factor; elevated expression of FOXC1 has been associated with poor prognosis in multiple malignancies, such as, hepatocellular carcinoma, pancreatic ductal adenocarcinoma, gastric cancer, and breast cancer." (PMID 39404228, 2024). "Next, using publicly available binding site data of ERα-associated TFs, we show that the identified core sites bound by FOXC1 in TNBC are bound by FOXA1 and NR2F2 in ER+ breast cancer." (PMID 39171293, 2024). "We have delineated the core, conserved function of FOXC1 in TNBC, and show that these core sites are parallelly regulated by FOXA1 in ER+ breast cancer." (PMID 39171293, 2024). "Compared with HER2+ and HR+ breast cancers, FOXA1 was lowly expressed in TBNC, while FOXC1, FOXK2, and FOXM1 were highly expressed." (PMID 36292640, 2022). "Among the TFs, the Alzheimer’s disease, basal-like breast cancer (BLBC), and tissue invasion are highly related with FOXC1 TF." (PMID 36016137, 2022). "We further identified corresponding targeting genes of TNBC-specific super-enhancers, including FOXC1, MET and ANLN, whose function and clinical relevance in breast cancer have been well documented." (PMID 34718356, 2022). "ChIP-qPCR on FOXC1 wt and knock-out BT549 basal-like breast cancer cells showed a correlation between trimethylation of H3K9, FOXC1 expression and loss of RNA PolII recruitment at the ESR1 regulatory sequence." (PMID 34831189, 2021). "In basal-like breast cancer, p65 and GATA3 were shown to promote and inhibit FOXC1 expression, respectively." (PMID 33854062, 2021).
breast carcinoma (continued). "Particularly, among the top 14 TFs, four (SR1, FOXA1, FOXC1, MYBL2) were among the TFs of the PAM50 gene signature (p = 1.46E-7, hypergeometric test), further indicating their role in regulatory mechanisms of breast cancer subtypes." (PMID 33558504, 2021). "In support of this, FOXC1 enhanced the DNA-binding ability of GLI2, evident by enhanced binding of GLI2 at the promoter of FAM38B gene, which is also markedly upregulated in breast cancer cells as a result of FOXC1 overexpression." (PMID 34572373, 2021). "Hierarchical clustering of NCS‐1 and breast cancer molecular markers showed a positive correlation with basal and proliferative markers, such as KRT5, 14 and 17, CDH3, FOXC1, FOXM1, EGFR, and MKI67." (PMID 31647602, 2020). "In another study, BRCA1 recruits GATA3 to the FOXC1 promoter to repress its expression in normal breast cells, inhibiting the development of the BLBC subtype of breast cancer." (PMID 30764547, 2019). "Several lines of evidence indicate that overexpression of FOXC1 contributes to these processes, perhaps most notably in studies of acute myeloid leukemia (AML) and basal-like breast cancer (BLBC)." (PMID 30764547, 2019). "Finally, FOXC1 may also underpin the EMT of breast cancer cells: FOXC1 expression is associated with an EMT gene signature in breast circulating tumor cells, while forced expression of FOXC1 in normal mammary epithelial cells induced a mesenchymal-like phenotype and downregulation of E-cadherin." (PMID 30764547, 2019). "BRCA_M14.n8 includes the hub gene SFRP1 as well as EGFR and FOXC1, PAM50 classifier genes used to define basal breast cancer (online)." (PMID 30993001, 2019). "In breast cancer, the metastatic effects of FLNB alternative splicing are mediated via the FOXC1 transcription factor." (PMID 31478829, 2019). "There is compelling evidence demonstrating that FOXC1 is aberrantly de-repressed in AML and breast cancer." (PMID 30764547, 2019). "FOXC1 is consistently and exclusively over-expressed in BLBC when compared to other breast cancer molecular subtypes in multiple, independent, gene expression microarray datasets." (PMID 29487724, 2018). "We found that breast cancer subtypes could be assigned with >90% diagnostic accuracy, as indicated by the area under the ROC curve of the partition tree, by differential expression analysis with respect to a normal breast tissue reference using only 4 genes: CBX7, ESR1, FOXC1, and FOXM1." (PMID 29868123, 2018). "We also added genes important for breast cancer biology or subtyping (ER, PGR, ERBB2, MKI67, AURKA and FOXC1)." (PMID 29973242, 2018). "For example, in luminal A breast cancer, EGFR and FOXC1 had 453 and 343 ceRNA connections, respectively and shared four miRNAs (miR-15b-3p, miR-141-3p, miR-200a-3p and miR-760)." (PMID 28052038, 2017). "For instance, in breast cancer, raised levels of PRC2 leads to high levels H3K27 methylation in the promoter regions of FOXC1, E-cadherin, RAD51, RUNX3 and CDKN1C (p57kip2)." (PMID 27845897, 2017). "Therefore, FOXC1 may be used as biomarker for treatment in breast cancers by tamoxifen." (PMID 28028927, 2017). "To further determine the effect of FOXC1 on Elf5 levels, we overexpressed FOXC1 in HC11 mouse mammary epithelial cells and T47D human breast cancer cells." (PMID 29070831, 2017). "In breast cancer, EGFR activation induced FOXC1 transcription and FOXC1 knockdown impaired cell proliferation and migration." (PMID 26198045, 2016). "FOXC1, FOXC2, and FOXQ1 are highly expressed in basal-like subtype breast cancer, but are less present in luminal subtype cancer." (PMID 25848863, 2015). "Expression of some MMPs correlated with FOXC1 expression, such as MMP7 in breast cancer and MMP1, MMP2, MMP7, and MMP9 in hepatocellular cancer." (PMID 24889262, 2014). "In the present study, five genes, ABCB1, FOXC1, GSTP1, PPP2R2B and RASSF1A were hypermethylated already in early stage breast cancer (stage I and II)." (PMID 24093668, 2013).
breast carcinoma (continued). "Breast cancer specific survival was significantly improved in patients with methylated promoters for ABCB1, GSTP1 and FOXC1 (p = 0.004, p = 0.004 and p = 0.021 respectively)." (PMID 20338046, 2010). "Three genes (FOXC1, EN1, and ELF5) stood out by displaying a pattern opposite to that of FOXA1, with hypomethylation and expression in Basal tumors, but hypermethylation and repressed expression in all other breast cancer subtypes." (PMID 40155623, 2025). "The top significant regulatory TFs (YY1, FOXC1, FOXL1, and MEF2A) may be responsible for the related pathways of the breast cancer cellular process of disease development." (PMID 39656775, 2024). "Finally, we show that core FOXC1 targets in TNBC are regulated in parallel by the pioneer factor FOXA1 and the nuclear receptor NR2F2 in ER + breast cancer." (PMID 39171293, 2024). "The expression of the majority of these FOXC1 targets (21/38) is prognostic (p value < 0.05) in predicting relapse-free survival of patients with ER/PR/HER2 negative breast cancer." (PMID 39171293, 2024). "Furthermore, NF-B induced the transcription factor Forkhead Box C1 (FOXC1), which is an upstream mediator of Hh signaling via upregulation of GLI2 expression in basal-like breast cancer cells." (PMID 35744786, 2022). "For instance, FOXC1, which is active in BCC-I, can activate SMO-independent HH signaling in basal-like breast cancer, suggesting that it may regulate BCC drug resistance." (PMID 35687691, 2022). "Moreover, the expressional levels of FOXC1 gene is negatively related with that of Polycomb group (PcG) genes, i.e., Bmi1, EZH2, and SUZ12, in breast cancer cells." (PMID 34167089, 2021). "Moreover, GLI1 (GANT61) but not SMO (GDC-0449 and LDE225) inhibition significantly reduced FOXC1-induced GLI-BS-luciferase activity in both SMO-positive and SMO-negative breast cancer cell lines, suggesting an SMO-independent activation of GLI." (PMID 34572373, 2021). "Additionally, the Forkhead Box C1 (FOXC1) transcription factor, an upstream mediator of Hh signaling via upregulation of GLI2 expression in basal-like breast cancer cells is induced by NF-κB." (PMID 31394751, 2019). "Although the EGFR-MAPK-PI3K pathway upregulates the expression, activity, and protein level of FOXC1, the how and why of FOXC1 being exclusively expressed in BLBC rather than in other breast-cancer molecular subtypes has yet to be answered." (PMID 29487724, 2018). "In general, it appears that the output of FOXC1 transcriptional regulation in non-BLBC subtypes of breast cancer differs significantly from that in BLBC." (PMID 29959321, 2018). "Unlike FOXA1, expression of FOXC1 correlates with the basal-like breast cancer subtype and predicts poor breast cancer patients outcome." (PMID 29864144, 2018). "In contrast, our functional studies demonstrate that higher FOXC1 levels significantly correlate with good prognosis in non-BLBC subtypes of breast cancer." (PMID 29959321, 2018). "Interestingly, higher expression of the FOXC1 signature conferred a significantly greater probability of relapse-free survival in only the Luminal B and HER2+ breast cancer patients." (PMID 29959321, 2018). "FOXC1 promotes metastasis and invasion by inducing MMP7 expression in breast cancer." (PMID 29552326, 2018). "Our previous study showed that there was high FOXC1 expression in basal‐like breast cancers (no or very low ERαα expression)." (PMID 28028927, 2017). "Our current data showed that there was a significant correlation between FOXC1 expression levels and ERα negative breast cancer and further supported previous conclusion." (PMID 28028927, 2017). "In the anthracycline-based patient group, breast cancer-specific DFS was significantly improved in patients without FOXC1 protein overexpression (P = 0.03)." (PMID 28493031, 2017).
breast carcinoma (continued). "Eleven of the 11 datasets from Oncomine, which contain gene chip profiles classified as normal or breast carcinoma tissues, showed that FOXC1 mRNA levels were much higher in ERα‐negative breast cancers than that in ERα‐positive breast cancers." (PMID 28028927, 2017). "In this study, we found that there was significantly higher FOXC1 expression in ERα‐negative breast cancer and ERα‐positive breast cancer." (PMID 28028927, 2017). "The forkhead box C1 (FOXC1) transcription factor, an important prognostic biomarker specific for BLBC, has been shown to be induced by EGF and is critical for EGF effects in breast cancer cells." (PMID 28629477, 2017). "Similar to NUMB, the EMT negative regulators GATA3 and FOXA1 had significantly lower expression in the BLBC subtypes and in ER-negative and higher histological grade breast cancer patients, whereas the EMT inducers FOXC1, FOXC2 and SNAI1 mimicked the expression profile of Notch1." (PMID 27506933, 2016). "Similar to NUMB, the EMT negative regulators GATA3 and FOXA1 had significantly lower expression in the BLBC subtypes, ER-negative and higher histological grade breast cancer patients, while the EMT inducers FOXC1, FOXC2 and SNAI1 mimicked the expression profiles of Notch1." (PMID 27506933, 2016). "To further confirm these results, we also investigated the expression of FOXC1 and FOXCUT in four hepatocellular cancer cell lines and five breast cancer cell lines, and found that both FOXC1 and FOXCUT expressions were higher in these cancer cells than in normal cells." (PMID 24889262, 2014). "Further, we identified four novel genes (ABCB1, FOXC1, PPP2R2B and PTEN) that were found to be already aberrantly methylated in DCIS (Ductal carcinoma in situ), a pre-invasive stage of breast cancer and that were also found to be methylated in the locally advanced breast cancers." (PMID 24093668, 2013). "In summary, along with the observation that FOXC1 and NR2F2 co-interact, it is likely that core binding sites of FOXC1 in TNBC identified here and represented by cluster 1 and cluster 4 peaks, are sites where FOXA1/NR2F2 are bound in luminal breast cancer (and vice versa)." (PMID 39171293, 2024). "FOXC1 and L1CAM may share common mechanisms in breast cancer progression." (PMID 38183514, 2024). "Otherwise, the transcription factor FOXC1 (Forkhead box C1 protein) mediates the activation of the SMO-independent Hedgehog signal by interacting and activating Gli2, thus inducing the activity of ALDH1 and promoting the self-renewal of CSCs in basal breast cancers." (PMID 37492224, 2023). "Similarly, in basal-like breast cancer (BLBC), FOXC1 may increase cancer stem cell (CSC) properties by cellular mechanisms." (PMID 36092920, 2022). "Using an independent clinically annotated breast cancer gene expression dataset, we confirmed the significant upregulation of FOXC1 in TNBC compared to non-TNBC in METABRIC cohort, and higher expression of FOXC1 correlates with poor overall survival of breast cancer patients." (PMID 33854062, 2021). "Consequently, the authors proposed that FOXC1-dependent activation of non-canonical Hedgehog signaling is a potentially significant contributor to CSC-like properties in breast cancers with high FOXC1 expression." (PMID 30764547, 2019). "While FOXC1 may operate as an anti-metastatic factor in non-BLBC breast cancer subtypes, it was unclear if EZH2-mediated repression of an anti-metastatic program through suppression of FOXC1 was subtype-specific." (PMID 29959321, 2018). "We demonstrate that higher FOXC1 is predictive of favourable outcome specifically in Luminal B breast cancer patients and establish the use of EZH2 methyltransferase inhibitors as a viable strategy to block metastasis in Luminal B breast cancer, where options for targeted therapy are limited." (PMID 29959321, 2018). "All results suggested that FOXC1 was overexpressed in ERα‐negative breast cancer cell lines." (PMID 28028927, 2017).